DMGDH (dimethylglycine dehydrogenase)
Description:
Catalyzes the demethylation of N,N-dimethylglycine to sarcosine. Also has activity with sarcosine in vitro.
Synonyms: ME2GLYDH; DMGDHD
Tractability: Small molecule: a structure with a bound ligand is known. PROTAC: its protein half-life has been measured.
Gene: Protein-coding gene on chromosome 5 (78,996,974 to 79,236,038, reverse strand). Ensembl gene ENSG00000132837.
Subcellular location: Mitochondrion
Subcellular location (Human Protein Atlas): Mitochondria
Pathways (Reactome):
Metabolism: Choline catabolism
Gene Ontology:
Molecular function: dimethylglycine dehydrogenase activity; RNA binding; electron transfer activity
Biological process: choline catabolic process; choline metabolic process; amino-acid betaine catabolic process
Cellular component: mitochondrion; cytoplasm; mitochondrial matrix
Genetic constraint (gnomAD): Loss-of-function variants: 78 observed, 99.99 expected, observed/expected ratio (o/e) 0.78, 90% interval 0.65 to 0.94. The upper end of that interval is the gene's LOEUF score, 0.94, which puts it in group 3 of 6, group 1 being the genes least tolerant of losing a copy. Missense variants: 982 observed, 1,086.6 expected, observed/expected ratio (o/e) 0.9, 90% interval 0.86 to 0.95. Synonymous variants: 345 observed, 384.38 expected, observed/expected ratio (o/e) 0.9, 90% interval 0.82 to 0.98.
Gene-disease validity (ClinGen):
ClinGen rates the evidence that DMGDH causes each of these diseases.
dimethylglycine dehydrogenase deficiency (autosomal recessive): Limited. An extremely rare autosomal recessive glycine metabolism disorder characterized clinically in the single reported case to date by muscle fatigue and a fish-like odor.
Homologues: Orthologues: chimpanzee DMGDH (99% identical), macaque DMGDH (98% identical), pig DMGDH (94% identical), dog DMGDH (92% identical), rat Dmgdh (90% identical), mouse Dmgdh (90% identical), guinea pig DMGDH (87% identical), tropical clawed frog dmgdh (79% identical), rabbit DMGDH (76% identical), zebrafish dmgdh (67% identical), Caenorhabditis elegans Y37E3.17 (32% identical). Paralogues in human: SARDH (32% identical), PDPR (31% identical), AMT (13% identical), FOXRED1 (12% identical), L2HGDH (10% identical), YPEL1 (4% identical), YPEL2 (4% identical), YPEL3 (4% identical), YPEL4 (4% identical), YPEL5 (3% identical).
Diseases named in the same sentence as DMGDH in open-access papers:
DMGDH is named in the same sentence as 17 diseases in open-access papers, as found by Europe PMC text mining. Sharing a sentence is not in itself a finding about the gene and the disease. The quoted sentences say what the papers report.
COVID-19 (2 papers, 2021 to 2023). A disease caused by infection with severe acute respiratory syndrome coronavirus 2. "Homozygous carriers of DMGDH A allele, which has been related to lower levels of selenium, in our study were less likely to present severe form of COVID-19 (OR 0.2, 95% CI 0.09–0.9, p = 0.03)." (PMID 34150833, 2021). "Therefore, we evaluated genetic determinants of vitamin D (DHCR7/NADSYN1 rs12785878, GC rs2282679, CYP2R1 rs10741657, VDR rs2228570), zinc (PPCDC rs2120019) and selenium (DMGDH rs17823744) as risk factors for severe forms of COVID-19." (PMID 34150833, 2021). "COVID-19 patients were genotyped for variants in DHCR7/NADSYN1, GC, CYP2R1, VDR, PPCDC and DMGDH genes." (PMID 34150833, 2021).
diabetes (2 papers, 2018 to 2023). "DMGDH gene is known to catalyze the conversion of glycine to sarcosine, and hypoglycemia is reported as a risk for developing diabetes." (PMID 36528847, 2023). "The gene Sardh, which showed a higher expression level in the gerbils with diabetes, is a flavoprotein that converts sarcosine back to glycine and catalyzes the conversion of dimethylglycine dehydrogenase (DMGDH) to sarcosine." (PMID 29394254, 2018).
dimethylglycine dehydrogenase deficiency (2 papers, 2016 to 2023). "However, the GCR of DMGDH, CD36 and GJB2, the variants on which were linked to diseases Dimethylglycine dehydrogenase deficiency, Platelet glycoprotein IV deficiency, and Deafness (autosomal recessive 1A), respectively, exhibited substantial variations across ethnic groups." (PMID 37985665, 2023).
hepatocellular carcinoma (2 papers, 2016 to 2022). A malignant tumor that arises from hepatocytes. "In our work, we performed RNA-seq for50 pairs of normal-tumor of hepatocellular carcinoma (HCC) samples and found that the expression of dimethylglycine dehydrogenase (DMGDH) is decreased in HCC." (PMID 27119355, 2016). "In addition, the GSE77314 database was once mined for the gene DMGDH, which inhibits metastasis in hepatocellular carcinoma, but the differential multiplicity of the gene did not meet the authors’ screening criteria; thus, it was filtered out." (PMID 35627170, 2022).
psoriasis (2 papers, 2024 to 2025). An autoimmune condition characterized by red, well-delineated plaques with silvery scales that are usually on the extensor surfaces and scalp. "We have recently found that common variants of SOD2, CAT, and dimethylglycine dehydrogenase (DMGDH) genes may influence the levels of selenium, another microelement associated with psoriasis." (PMID 40002942, 2025). "The only result that was of note was the observation that blood selenium levels were significantly lower for carriers of the CC variant of SOD2, CAT, and DMGDH, which may be a generalized effect of these polymorphisms and the association between Se and psoriasis." (PMID 38791044, 2024).
Insulin resistance (1 paper, 2019). Increased resistance towards insulin, that is, diminished effectiveness of insulin in reducing blood glucose levels. "On the contrary, a genetic variant in DMGDH, causing lower DMGDH, was significantly associated with increased plasma insulin, increased HOMA index of insulin resistance, and increased risk of incident T2DM." (PMID 31208147, 2019).
tumor (1 paper, 2016). "We found that in ~80% samples, the DMGDH protein level in tumor tissue was significantly higher than that of normal tissue." (PMID 27119355, 2016). "In summary, we detected a novel tumor suppressor gene, DMGDH, as a biomarker that is capable of distinguishing between normal and tumor tissue, and this gene also suppresses metastasis in vitro, in vivo, and in clinical observations." (PMID 27119355, 2016). "Although the role of DMGDH suppression of tumor motility both in vivo and in vitro was validated by our previous experiments, the mechanisms underlying the suppression were still unclear." (PMID 27119355, 2016).
DMGDH also shares sentences with these, for which no sentence is quoted: aminoacylase 1 deficiency (1 paper); Arthritis (1); aspartylglucosaminuria (1); atherosclerosis (1); cancer (1); Hepatic steatosis (1); hyperprolinemia type 1 (1); Hypoglycemia (1); mesothelioma (1); metabolic disorders (1).